DOT1L (DOT1 like histone lysine methyltransferase)
Diseases named in the same sentence as DOT1L in open-access papers (continued):
Sharing a sentence is not in itself a finding about the gene and the disease.
leukemia (continued). "For example, fusions between the MLL protein and several transcription factors recruits DOT1L to gene promoters in MLL-leukemias, leading to altered gene expression." (PMID 28445939, 2017). "Previous biological studies have shown that H3K79 methyltransferase DOT1L is a drug target for MLL-rearranged leukemia." (PMID 26970896, 2016). "Therapeutic targeting of Dot1L enzymatic activity has provided a potential therapy strategy for MLL leukemia." (PMID 27007052, 2016). "The involvements and therapeutic potential of targeting PMTs in human cancer were initially illustrated in MLL leukemia where the recruitments of DOT1L by MLL-AF10 and PRMT1 by MLL-EEN were required for transcriptional deregulation and cellular transformation." (PMID 26766589, 2016). "Because of DOT1L’s crucial role in oncogenesis and maintenance of MLL-rearranged leukemia, much effort has been dedicated to find small molecule inhibitors of DOT1L." (PMID 27316347, 2016). "This led to the finding that the DOT1L inhibitors sensitize MLLr leukemias to BCL-2 inhibition with ABT-199." (PMID 26711339, 2015). "DOT1L is an anti-cancer therapeutic target in leukaemia but has apoorly understood role in solid tumours." (PMID 26199140, 2015). "The slow anti-proliferation activity for the DOT1L inhibitors was also observed in previous studies against MLL leukemia." (PMID 25359765, 2014). "SYC-522 is a potent inhibitor of DOT1L and represents a useful probe for studying the biological functions of DOT1L in MLL-rearranged leukemia." (PMID 24858818, 2014). "DOT1L activity in MLL-rearranged leukemia leads to H3K79 hypermethylation, resulting in aberrant expression of genes related to hematopoietic cell stemness and self-renewal." (PMID 24858818, 2014). "Preclinical studies of MLL-rearranged leukemias have demonstrated a critical role of this enzyme for leukemogenesis, as well as preferential leukemia cytotoxicity with DOT1L inhibition (e.g., EPZ004777)." (PMID 24672775, 2014). "The enzymatic activity of the histone methyltransferase DOT1L has been shown to be essential for MLL-R leukemia in several studies." (PMID 23847761, 2013). "Several components of the transcriptional activation complex in MLL-R leukemia are being targeted: menin, bromodomains, and the methyltransferase DOT1L." (PMID 23847761, 2013). "Compelling evidence links recruitment of the histone methyltransferase DOT1L to transcriptional activation of oncogenes such as HOXA9 in MLL-R leukemia." (PMID 23847761, 2013). "In early experiments, a highly specific DOT1L KMT inhibitor appears to disrupt the growth of MLL-FP leukemias." (PMID 24213472, 2012). "The clearest example of this currently is the exciting development of DOT1L inhibitors for MLL-translocated leukemias described here." (PMID 21811504, 2012). "Identification of the molecular mechanisms of derepression by human DOT1L will be crucial for understanding the role of DOT1L in leukemias bearing MLL and CALM fusion proteins." (PMID 21291527, 2011). "Such sgRNA-tiling screen paired with single-cell transcriptional profiling could uncover specific sub-domain regulatory elements in the candidate protein DOT1L that regulates resistance against anti-DOT1L therapy in a leukemia subtype." (PMID 41394966, 2025). "Due to its essential function in KMT2A-r leukemia, DOT1L is regarded as a vital therapeutic target." (PMID 40361241, 2025). "Menin functions as an obligate chromatin scaffold, anchoring KMT2A (MLL) fusion complexes to HOX loci in concert with LEDGF and the SEC/DOT1L machinery, sustaining a HOX/MEIS-high transcriptional state that defines KMT2A-rearranged leukemia and ∼30% of NPM1-mutated AML." (PMID 41347170, 2025). "Inhibition of DOT1L has emerged as a promising therapeutic strategy for KMT2Ar leukemias." (PMID 39682203, 2024).
leukemia (continued). "Despite the promising mechanism, clinical trials of DOT1L inhibitors as monotherapy have shown limited efficacy, particularly in achieving durable remissions, likely due to the redundancy of oncogenic pathways in KMT2Ar leukemias." (PMID 39682203, 2024). "On the other hand, mutated DOT1L mimicking constitutive acetylation (K358Q) can rescue the growth deficiency of MLLr leukaemia cells with ATM loss, which validates our speculation that DOT1L serves as a downstream target of ATM." (PMID 38671157, 2024). "Moreover, when made to work together, SIRT1 activators and DOT1L inhibitors exhibit increased antiproliferative action against KMT2A‐r leukemia cells." (PMID 39428967, 2024). "Just as certain types of leukaemia hijack DOT1L to open up novel gene expression programs and pathways, we speculate that epigenetic regulators like DOT1L may have been similarly used to drive the evolution of novel immune differentiation pathways." (PMID 38962004, 2024). "Notably, the interaction of LAMP5-AS1 with DOT1L regulates H3K79 methylation directly at LAMP5 locus, which sheds light on the complexity and underlying mechanism of MLL leukemia." (PMID 38374003, 2024). "Therefore, DOT1L is considered as a new therapeutic target against MLL‐rearranged leukemia and the corresponding inhibitors are investigated in clinical trials." (PMID 39307938, 2024). "HOXA9 transcription is dependent on DOT1L-mediated H3K79 methylation in KMT2A-r leukemia." (PMID 38601080, 2024). "Analysis from the TCGA database displayed that DOT1L was highly expressed in lymphoma and leukemia." (PMID 39307938, 2024). "DOT1L stabilized by glucose metabolism was found to regulate the expression of homeobox A9 (HOXA9) and meis homeobox 1 (MEIS), an effect associated with the proliferation of MLL-fusion leukemia." (PMID 39394462, 2024). "To examine the utility of CRISPR-SADD as a generally applicable tool for pharmaceutical development, we selected additional leukemia therapeutic target proteins (DOT1L, MOF, and LSD1) that their drug-protein binding has been previously defined by cocrystallization." (PMID 38394203, 2024). "Although DOT1L is implicated in promoting leukemia development, and EPZ5676 monotherapy has shown promise in MLL-fusion leukemia, its effectiveness relies on the epigenetic repression of MLL target genes and continuous intravenous infusion to maintain therapeutic concentrations." (PMID 38672640, 2024). "On the other hand, whether Dex regulates DOT1L expression in MLL‐rearranged leukemia cells has aroused our great interest." (PMID 39307938, 2024). "Because H3K79me2 is deposited exclusively by DOT1L, this major finding also suggests a possible feed-forward loop in leukemias driven by MLL1-DOT1L fusion, which may support combined menin-MLL1 and DOT1L inhibitor therapy." (PMID 39403928, 2024). "Targeting DOT1L with inhibitors like pinometostat (EPZ-5676) has shown promise in MLL-rearranged leukemia xenograft models, achieving significant tumor regression, while in the clinical setting, although well tolerated, pinometostat has shown modest clinical activity in adult leukemia (NCT01684150)." (PMID 39766049, 2024). "In contrast, the proliferation of normal human CD34 + cells was unaffected under the conditions where that of P31/FUJ cells was severely impaired, suggesting that the combined inhibition of MOZ/MORF KATs and DOT1L KMT selectively induces differentiation of CALM-AF10 leukemia cells." (PMID 37031220, 2023). "Binding of DOT1L to KMT2A fusion proteins causes inappropriate H3K79 hypermethylation at KMT2A target genes, leading to an altered transcriptomic landscape that strongly favors leukemia development." (PMID 37740239, 2023). "Many cancers, especially mixed lineage leukemia, are related to Dot1l." (PMID 36639782, 2023).
leukemia (continued). "Undoubtedly, these findings could be utilised to target regulatory enhancer axes, and/or key epigenetic enzymes such as DOT1L or LSD1 in LSC from MLLr‐or other leukaemia subtypes (discussed further in therapy section)." (PMID 37872885, 2023). "These phenotypes were dependent on the main complex partners that have also been identified in human leukemia and could be rescued by genetic or chemical targeting of DOT1L." (PMID 37720104, 2023). "Likewise, targeting interactions between KMTA2 fusion partners and DOT1L emerged as a valid strategy against KMT2Ar leukemia." (PMID 37325571, 2023). "For future drug development, more needs to be understood about exactly how DOT1L contributes to leukemogenesis, the role of its enzymatic methyltransferase activity, and how leukemias might develop resistance." (PMID 37740239, 2023). "Recently, DOT1L has become an attractive therapeutic target for MLL-rearranged leukemias." (PMID 35331314, 2022). "Recently, DOT1L has become a popular therapeutic target for MLL-rearranged leukemias." (PMID 35331314, 2022). "Recently, many small molecule PPI inhibitors, such as MLL1-menin and MLL1-WDR5 interaction inhibitors, were synthesized and entered into clinical trials for AML, suggesting that PPIs involving DOT1L may have similar potential for MLL-rearranged leukemias." (PMID 35331314, 2022). "Although these DOT1L inhibitors were used in leukemia treatment, they might be potentially therapeutic based on their important role in solid tumors." (PMID 36376832, 2022). "The exact mechanism of function of DOT1L in these contexts remains elusive, however there is compelling evidence showing histone methylation by DOT1L activates subsets of genes involved in hematopoietic stem cell (HSC) development that is coopted by leukemia cells in various AML subtypes." (PMID 35712672, 2022). "The prominent role of DOT1L in MLLr leukemia has led to the development of targeted therapies." (PMID 35712672, 2022). "Based on the anti-tumor effects of DOT1L inhibitors in MLL-rearranged leukemia and thymic lymphoma, we also investigated whether DOT1L inhibitor treatment alone or in collaboration with HDAC inhibitors reduces viability of CTCL cells." (PMID 36425063, 2022). "Here, we review the recent advances and future trends of various therapeutic strategies against DOT1L for MLL-rearranged leukemias, including DOT1L enzymatic activity inhibitors, DOT1L degraders, protein–protein interaction (PPI) inhibitors, and combinatorial interventions." (PMID 35331314, 2022). "Activation of NFκB, the outcome of telomere complex damage, is present in leukemia stem cells but absent in normal stem cells and can activate DOT1L which has been linked to MLL-fusion leukemias." (PMID 34736527, 2021). "Preclinical studies using genetic or small molecule inhibitors demonstrated that DOT1L methyltransferase activity is required for MLL-fusion–mediated leukemogenesis and validated DOT1L as a promising therapeutic target for the treatment of MLL-rearranged leukemia." (PMID 33562706, 2021). "In addition to its known role in MLLr leukemia, DOT1L plays a part in other cancers such as prostate cancer and multiple myeloma." (PMID 34500733, 2021). "In addition to leukemia, DOT1L has been reported as a potential therapeutic target in other solid tumors including breast and prostate cancer." (PMID 34887387, 2021). "This double-edge effect of DOT1L, in promoting leukemia and antagonizing reprogramming harmonizes with the view of cancer transformation as an incomplete reprogramming event in a post-stem cell that maintains some phenotypic traits of its developmental stage of origin." (PMID 34736527, 2021). "In most MLL-rearranged leukemia models, the response to DOT1L inhibitors is limited." (PMID 34201935, 2021). "Therefore, DOT1L histone methyltransferase is a potential target in the treatment of leukemia patients." (PMID 34500733, 2021).
leukemia (continued). "Notably, after treating MV4;11 cells with 100 nM inhibitor for 7 days we observed no discernable effect on the expression of HOXA9 and MEIS1, despite the emphasis on these genes as the critical mediators of DOT1L’s effects in MLL-r leukemia." (PMID 34263728, 2021). "PRC2 function is an ancillary pathway dependent on DOT1L and necessary for leukemia proliferation." (PMID 34263728, 2021). "However, in Δ10-DOT1L and I867A-DOT1L leukemia cells, we observed significantly decreased localization of DOT1L to these loci." (PMID 33562706, 2021). "Little is known about why MLL-r leukemia cell lines have such disparate sensitivities to DOT1L inhibitors or how MLL-fusions might cooperate with co-occurring lesions." (PMID 34263728, 2021). "Both 1° AML-3 and 1° MPAL-1 carry a KMT2A–AF9 fusion protein, whereas KOPN-8 carries a KMT2A–ENL fusion, suggesting that the AF9 fusion partner recruits particularly high levels of DOT1L to oncoprotein target loci while other leukemias can be variable for DOT1L recruitment." (PMID 34663924, 2021). "DOT1L has emerged as a therapeutic target in patients with MLL-driven leukemia." (PMID 33562706, 2021). "Thus, there is a need to find new potent inhibitors of DOT1L for the treatment of rearranged leukemias." (PMID 34500733, 2021). "Collectively, these data suggest that FLT3-ITD may represent an important pathway through which DOT1L inhibition reduces leukemia cell survival." (PMID 34263728, 2021). "In this study, we reported that LAMP5-AS1 is necessary for cell self-renewal in MLL leukemia in view of its capacity to enhance the methyltransferase activity of DOT1L, which facilitates H3K79me2 and H3K79me3 modifications on the locus of the HOXA genes to upregulate their expression." (PMID 32552847, 2020). "Moreover, additional leukemia subtypes, including MLL-PTD, IDH1/2-, NPM1-, and DNMT3A-mutated subtypes, were found to be sensitive to DOT1L inhibition, strengthening the importance of DOT1L methyltransferase activity for leukemic cells irrespectively of MLL-r." (PMID 32698374, 2020). "Although this discovery has led to a clinical trial of the DOT1L inhibitor EPZ-5676 for the treatment of leukemias harboring a rearrangement of the MLL gene, existing DOT1L inhibitors did not sufficiently suppress breast tumor growth and metastasis in an earlier study." (PMID 32244385, 2020). "Given that cell lines were exposed to compounds for only 3 days and DOT1L inhibitors are well documented to act very slowly in MLL-rearranged leukemia, we validated and extended this observation in a panel of 14 MM cell lines using growth assays with a duration of 2-3 weeks." (PMID 32215184, 2020). "The oncogenic drive of KMT2A-rearranged leukemia is dependent on the activation of DOT1L." (PMID 32050659, 2020). "Furthermore, we consistently identified missplicing (specifically intron retention) of key genes implicated in the pathogenesis of MLL-rearranged leukemia, namely SETD1A and DOT1L." (PMID 32398749, 2020). "Moreover, DOT1L was found to be significantly associated with the initiation and progression of the mixed-lineage leukemia (MLL)-rearranged leukemia and other solid tumors." (PMID 33363525, 2020). "In this regard, an inhibitor of DOT1L (pinometostat) has recently entered clinical trials in leukemia, and it may be possible to see if this agent also inhibits NSUN2." (PMID 32708015, 2020). "Considering that Dot1L and COMPASS complexes are linked to leukemia, these findings may help in the design of inhibitors that could serve as effective therapeutic agents." (PMID 32850785, 2020). "In addition, DOT1L inhibitor-induced losses of H3K79me at enhancers in leukemia cells has been correlated with reduced levels of H3K27 acetylation and reduced chromatin accessibility (probed by ATAC-seq)." (PMID 32781660, 2020). "However, expression of specific genes, such as HOXA9 and MEIS1, is strongly dependent on DOT1L specially in leukemias induced by MLL-fusion proteins." (PMID 33104701, 2020).
leukemia (continued). "Thus, several nucleoside-class DOT1L inhibitors have been developed, and have culminated in a clinical trial investigating leukemia harboring rearrangements in the MLL gene." (PMID 33379275, 2020). "We wondered whether LAMP5-AS1 affected self-renewal in MLL leukemia cells by regulating the methyltransferase activity of DOT1L." (PMID 32552847, 2020). "Of note, other subtypes of leukemia that show a high dependency on wild-type MLL1, like NPM1-, DNMT3A-, and IDH1/2-mutated as well as NUP98-rearranged AML, have been shown to be likewise sensitive to inhibition of DOT1L." (PMID 33371192, 2020). "This is the first study that a lncRNA regulates the self-renewal program and differentiation block in MLL leukemia cells by facilitating the methyltransferase activity of DOT1L and global H3K79 methylation, showing its potential as a therapeutic target for MLL leukemia." (PMID 32552847, 2020). "DOT1L plays an essential role in the development of MLL leukemia." (PMID 32552847, 2020). "Finally, although the involvement of DOT1L in leukemia was initially linked to its mislocation due to MLL fusion proteins, some of the most recent works demonstrated a role of DOT1L also in non MLL-rearranged leukemias." (PMID 31803695, 2019). "Overall, our study demonstrates that MLL1 fusions may also be prevalent in solid tumors, and the DOT1L‐dependent treatment strategy used in leukemia should be applicable to these tumors." (PMID 30548174, 2019). "Such inhibitors may lead to enhanced treatment outcomes for MLL-R leukemia, along with cytotoxic chemotherapy or DOT1L inhibitors." (PMID 31717699, 2019). "Given numerous studies demonstrating the importance of aberrant DOT1L function in the pathogenesis of MLL-rearranged ALL and genetic studies demonstrating a dependency on DOT1L in these leukemias, more recent attention has focused on the development and preclinical validation of DOT1L inhibitors." (PMID 35582725, 2019). "Impressive results have been obtained in preclinical studies investigating pharmacologic inhibition of DOT1L, and the DOT1L inhibitor Pinometostat entered a phase 1 clinical trial to treat pediatric patients with relapsed/refractory leukemias bearing a rearrangement of the MLL gene (NCT02141828)." (PMID 31803695, 2019). "For example, it will be interesting to determine whether and under which conditions HDAC1 activity influences DOT1L activity in human MLL‐r leukemia and whether the crosstalk is involved in the response of CTLC to HDAC inhibitors in the clinic." (PMID 31304633, 2019). "Furthermore, it has been shown that aberrant DOT1L activity in the context of leukemias with MLL-AF4 fusions results in aberrant H3K79 methylation of the gene encoding the anti-apoptotic protein BCL-2." (PMID 35582725, 2019). "Importantly, DOT1L inhibitor EPZ5676 was studied in phase I clinical trials for the treatment of pediatric patients with relapsed/refractory leukemias bearing a rearrangement of the MLL gene (ClinicalTrials.gov Identifier: NCT02141828 and NCT01684150)." (PMID 31888761, 2019). "Therefore, in MLL-rearranged leukemias, DOT1L is recruited on MLL target sites, and its mislocated enzymatic activity promotes the leukemic gene expression program." (PMID 31803695, 2019). "Indeed, in MLL-AF9-mediated mouse AML studies, inhibition of either SALL4, DNMT1, LSD1, or DOT1L completely blocked leukemia initiation and significantly delayed disease progression in vivo." (PMID 29308206, 2018). "DOT1L is therefore involved in leukemogenesis, especially in leukemias mediated by MLL fusion partners such as AF4, AF9, AF10 and ENL, which account for two-thirds of all MLL-linked leukemias." (PMID 29495487, 2018). "DOT1L encodes a HMT that methylates lysine-79 of histone H3, involved in the regulation of various cellular processes, such as development, reprogramming, differentiation or proliferation, and controls the development of diseases, including leukemia." (PMID 29721185, 2018).